TGFB1 (transforming growth factor beta 1)
Diseases named in the same sentence as TGFB1 in open-access papers (continued):
Sharing a sentence is not in itself a finding about the gene and the disease.
cancer (continued). "Additionally, they present promising potential therapeutic opportunities in cancer treatment, including in response to chemoresistance and subsequent BCa recurrence, targeting the TGFβ1/lncRNA-LET/miR-145 axis." (PMID 35646642, 2022). "A potential contributor to dormant cancer cell reawakening may be the loss of TSP-1 around sprouting endothelial cells, which accelerate tumor cell outgrowths through TGFβ1 and periostin." (PMID 35884405, 2022). "Cancer cells subjected to TGFβ1 treatment was found to become more motile and invasive." (PMID 36463238, 2022). "Although emodin is reported to inhibit TGFβ1 signalling, the suppressive effects of emodin on TGFβ1-associated cancer cachexia have not been previously investigated." (PMID 35406121, 2022). "TGFβ1 signalling upregulates TCF4 expression in cancer cells." (PMID 35406121, 2022). "Moreover, negative regulatory genes of cancer-immunity cycle (CIC) illustrated that immunosuppressors TGFB1, VEGFA, and CD274 (PDL1) were all positively correlated with risk-scores." (PMID 35222383, 2022). "Indeed, SULF2 protein levels were elevated in LX-2 cells challenged in vitro with exogenous TGFβ1, with a strong and a highly significant correlation in gene expression between the two confirmed in the cancer genome atlas (TCGA) HCC dataset." (PMID 36589727, 2022). "Importantly, EZH2-mediated SMAD3 methylation not only rendered cancer cells more vulnerable to TGFB1 and promoted cancer cell EMT and metastasis, but also showed a positive correlation with poor patient survival." (PMID 35085106, 2022). "Specifically, according to canonical markers, the three quantity-predominant major components (i.e., c1, c2, and c4) were defined as cancer-associated myofibroblasts (CAFmyo), inflammatory CAFs (CAFinfla), and adipogenic CAFs (CAFadi) by over-presenting ACTA2, FAP/TGFB1, and CFD, respectively." (PMID 36333338, 2022). "Interestingly, the ‘cell adhesion molecule binding’ group includes proteins associated with ‘TGFB1 signaling’ which is reported to promote EMT and invasion in advanced stages of cancer." (PMID 36505879, 2022). "The obtained results may confirm the contribution of the TGFB1 in increasing the migratory capacity of cells and the formation of secondary cancer foci in distant organs." (PMID 35798776, 2022). "Previous studies reported that TGFβ1 promoted EMT in cancer cells." (PMID 34096887, 2021). "Notably, inhibition of TGFβ1 can prevent CRC metastasis by unleashing a cytotoxic T cell response against cancer cells, implying that TGFβ1 signaling suppresses cancer recognition by the immune system." (PMID 34975867, 2021). "Furthermore, overexpression of RUNX1 in the cancer cells is mediated by Transforming Growth Factor Beta-1 (TGFβ1) and thrombospondin 1 (TSP1)." (PMID 34376784, 2021). "Thus, our results supported previous findings and provided a novel functional mechanism of TGFB1 in cancer aggressiveness." (PMID 34307149, 2021). "This was mainly based on the exploring that the inhibition of SMAD4 simultaneously with the decreased TGFβ1 reduces the formation of highly invasive cancer spheres in PCs, decreases clonogenicity, and invasiveness of cancer cells and leads to increase in EMT-related properties." (PMID 34012911, 2021). "In fact, TGFβ-induced EMT increases cancer stem-like cells in PANC-1 cells, which fits observations that side population cells could be isolated from monolayers of PANC-1 but not E type BxPC-3 cells and predominate in TGFβ1-induced EMT and invasion." (PMID 34771704, 2021). "We report that EGR1 is also upstream of E2-induced TGFβ1 transcription in primary human dermal fibroblasts, which is not surprising as EGR1 binds to and activates the TGFβ1 promoter and exogenous expression of EGR1 in the cancer cell line HT1080 led to increased secretion of TGFβ1." (PMID 33640015, 2021).
cancer (continued). "We speculated that the expression of TGFβ1 in hepatocytes could be induced by secreted factors from the cancer cells, which are under the transcription control of RUNX1." (PMID 34376784, 2021). "Six overexpressed oncogenes including BCL2, NOTCH1, SOX4, and CTNNB1 and 10 downregulated tumor suppressor genes including PRKCB, IRF1, CYLD, and TGFB1 were identified as the targets of the DE miRNAs, which may promote cancer development." (PMID 34336826, 2021). "TGFβ1 is a crucial factor in interactions between cancer cells and surrounding stromal fibroblasts." (PMID 34095135, 2021). "TGFβ1 is among TGFβ members that modulate RUNX1 expression in cancer cells." (PMID 34376784, 2021). "In addition, it was aberrantly activated in the late-stages of tumorigenesis and the dysregulation of TGFβ1 signaling pathway contributed to various aspects of cancer progression." (PMID 33995472, 2021). "The abundant co-expression of TRDV2 and TGFB1 transcripts in AML suggests that a suitable environment may be present in this cancer to favor TGF-β conditioning of Vγ9Vδ2 T cells." (PMID 35028614, 2021). "TGFβ1, a member of the TGFβ family of growth and differentiation factors, controls cell differentiation and proliferation and plays key roles in skeletal diseases, fibrosis, and cancer." (PMID 33707345, 2021). "Notably, the hedgehog signaling cross-talking with TGFβ1 cascades has been reported in cancer development and metastasis." (PMID 33430164, 2021). "The mechanism(s) in which transforming growth factor beta 1 (TGFβ) modulates autophagy in cancer remain unclear." (PMID 34760883, 2021). "Interestingly, however, this cell cycle arrest promoted by TGFβ1 has been related to drug resistance in different cancers, including cSCC, as a consequence of the direct repression of specific genes related to cell cycle progression by Smad2/3 proteins." (PMID 34830768, 2021). "Next, we asked whether RUNX1 expression in cancer cells was affected by the presence of TGFβ1 or TGFβRII in vitro." (PMID 34376784, 2021). "The role of TGFβ1 in cancer is complex and has been reported in many studies." (PMID 34095135, 2021). "We recently employed two human cancer cell lines with high autocrine TGFβ1 (aTGFβ1) production, namely Panc1, a PDAC-derived line with a quasi-mesenchymal signature, and MDA-MB-231, a TNBC-derived line of the basal-like subtype, to elucidate the underlying signaling pathways." (PMID 33802809, 2021). "Moreover, there is a direct relationship between TGFβ1 levels and metastatic burden in a variety of cancers." (PMID 34768810, 2021). "Additionally, TGFβ1 plays an important role in inducing epithelial–mesenchymal transition in cancer cells and stimulates immune suppression signals as well as premetastatic niche generation." (PMID 34071145, 2021). "The cancer cells with silenced-TSP1 were failed in stimulating TGFβ1 expression in hepatocytes." (PMID 34376784, 2021). "TGFβ1 treatment in human cancer cells significantly suppressed PAQR5 expression." (PMID 35127538, 2021). "Furthermore, suppression of TGFβ1 signaling in NK cells reduced metastases in two murine models of cancer (B16-F10 melanoma and RM-1 prostate adenocarcinoma)." (PMID 34768810, 2021). "Despite these promising results in preclinical cancer models, targeting TGFβ1 in the postoperative period may have adverse effects related to wound healing, as TGFβ1 is known to play a role." (PMID 34768810, 2021). "While important cancer drivers such as TGFB1 and KRAS exhibited wide intratumoral expression." (PMID 32642694, 2020). "Furthermore, we showed that there is strong correlation between the METTL3/TGFβ1/Snail axis and cancer progression in lung metastasis potential cancer cell models." (PMID 31991845, 2020).
cancer (continued). "We started with trajectory reconstruction on the time-series datasets of an OVCA420 cancer cell line undergoing EMT induced by three different external signal (TGFB1, EGF, and TNF) and uncovered the existence of multiple ICSs displaying hybrid epithelial and mesenchymal features." (PMID 33488673, 2020). "Although treatment of TGF-β or active PLK1 upregulates TSG6 expression, the depletion of TSG6 reduced the levels of PLK1 or TGFB1, suggesting that TSG6 and PLK1 or TGFB1 could mutually trigger their expression for cancer metastasis." (PMID 31548612, 2020). "The data obtained in this study reveal that RAC1B effectively inhibits TGFβ1-dependent cell motility of mesenchymal subtype carcinoma cells by promoting protein expression of the inhibitory Smad, SMAD7, via intermittent transcriptional induction of the deubiquitinating enzyme, USP26." (PMID 32545415, 2020). "As in other cancers, we observed high expression of TGFB1 and TGFB3 in Group 3 MB." (PMID 31328883, 2019). "Interestingly, the signaling between the cancer cells and the mesothelial cells appears to be reciprocal, since interactions with the mesothelial cells also induce increased TGFβ1 in cancer cells." (PMID 31640297, 2019). "TGFβ1 also induces the expression of BRACHYURY in human carcinoma cells." (PMID 31248450, 2019). "The expression analysis of the genes belonging to TGFβ1 signaling pathway after treatment with nanocurcumin revealed that this agent can mediate the suppression of telomerase via triggering TGFβ1 pathway, representing the promise of this formulation of curcumin to be used against cancer cells." (PMID 28992682, 2018). "TGFβ1 is able to promote the migration and invasion of cancer cells through the induction of EMT." (PMID 30174709, 2018). "Taken together, our data suggest that TGFβ1 could be one of the candidates of immunosuppressive factors in cancers, and that TGFβ1 has a potential to promote cancer growth together with Treg cells." (PMID 29594353, 2018). "TGFβ1/Smad2/3 cascade signaling plays an important role in the EMT of cancer cells." (PMID 30174709, 2018). "TGFβ1/SMAD pathway is well known to contribute to cancer development and progression." (PMID 29495357, 2018). "Therefore, future multi-color immunohistochemistry will be required for more-detailed in situ characterization of TGFβ1+ dendritic-shaped cells in cancer tissues." (PMID 29594353, 2018). "Epidermal growth factor (EGF) and Transforming growth factor beta 1 (TGF-β1) act as potent drivers of cancer progression through the induction of epithelial-mesenchymal transition (EMT), in which epithelial cells acquire a mesenchymal phenotype and gain cancer stem-cell-like properties." (PMID 30347648, 2018). "Furthermore, in NIH3T3/635 cells after 3D co-culture with cancer cells, a trend of increasing expression was found with Tgfb1 and significantly decreased levels of caveolin-1 mRNA were observed." (PMID 29435153, 2018). "Interestingly, TGFβ1 was increased in subcutaneous AT from cancer cachectic patients, and it was up-regulated in the whole tissue samples, as well as in the isolated adipocytes." (PMID 28288584, 2017). "For the upregulation from primary to metastasis fibroblasts by TGFβ1 and TGFβ2, this may be because the role of TGFβ is strongly context-dependent in the metastatic progress, including cell and cancer type." (PMID 29221185, 2017). "Our findings demonstrating the joint power of TNFα + TGFβ1 + the factors they induce in MSCs on cancer cells provide proof-of-concept to the fact that MSCs are strongly affected by their microenvironment, and as a result secrete soluble mediators that modify their surroundings." (PMID 28553282, 2017). "CAFs could also respond to leptin to increase TGFB1 for paracrine signalling thus targeting TGFB1 and leptin signalling could target both cancer cell and CAF contributions to these synergistic metastatic pathways in tumors." (PMID 28542577, 2017).
cancer (continued). "Indeed, in this study we found that all of the cancer cell lines studied expressed TGFβ1 to some extent." (PMID 28239749, 2017). "A remarkable difference was revealed between MCF-7 cells exposed to CM derived from TNFα + TGFβ1-stimulated MSCs (Group 4) and cancer cells exposed to the two other relevant treatments: CM of vehicle-treated MSCs (Group 3) or to the two cytokines only (Group 2)." (PMID 28553282, 2017). "Thus, β-HCG has been suggested to exert tumorigenic actions by blocking the apoptotic effect of TGFβ1 in cancer cells of different origin by TGFβ receptor binding." (PMID 28754015, 2017). "Moreover, genes encoding CAF secretory factors that promote cancer cell invasion and disease progression, including CXCL12, TGFβ1, and PDGFα, were upregulated in CSC-derived fibroblasts." (PMID 28754894, 2017). "Because strict regulation of these processes is vital to maintaining cellular homeostasis and tissue integrity, dysregulation of TGFβ1 expression and activity has significant pathologic consequences and contributes to a number of disease states, including many cancers." (PMID 27589814, 2016). "TGFβ1, produced by cancer and stromal cells, is primarily involved in the desmoplastic reaction, but it may also support or antagonize cancer cell survival and dissemination." (PMID 27655713, 2016). "Several studies reported the nanocarrier-based targeting of the cancer biomarkers such as, transforming growth factor-beta-1 (TGF-β1), transmembrane receptor P185(HER2) for targeted cancer therapy, to our knowledge, none of these studies utilized to target the ROS using antioxidant peptide (Pep-A)." (PMID 26900409, 2016). "As is the case for TGFβ1, the calcium binding proteins S100A8/A9 are dual faced molecules that are not only involved in PDAC growth and dissemination, but can also form complexes with TGFβ1 thus concurring in further enhancing the spectrum of the effects evoked in cancer cells by this cytokine." (PMID 27655713, 2016). "The axis had been demonstrated to be involved in many kinds of cancer-related processes, like facilitating cancer cell growth and modulating cell cycle through TGFβ1 or β-catenin pathways, respectively, and participating in cellular growth and proliferation associated with FOXA1/2." (PMID 27167111, 2016). "Indeed, several TGFβ1 pathway inhibitors have been or are currently being tested in clinical trials for various cancer types." (PMID 27589814, 2016). "This mutational landscape might influence cancer cells response to EGF, Transforming Growth Factor β1 (TGFβ1) and stromal inflammatory calcium binding proteins S100A8/A9." (PMID 27655713, 2016). "Although its influence on multiple cell types is critical for the regulation of numerous biologic processes in the host, dysregulation of both TGFβ1 expression and activity is frequently observed in cancer and contributes to various aspects of cancer progression." (PMID 27589814, 2016). "However, miR-17-92-mediated blunting of signal transduction by TGFβ, by down-regulating its signaling components, would enhance cell proliferation and make cancer cells refractory to TGFβ1 signaling." (PMID 26442266, 2015). "TGFβ1, which induces various cellular responses in a context-dependent manner, may function not only as a growth suppressor but also as a promotor of cancer depending on the disease stage." (PMID 25826092, 2015). "Additionally, inhibition of TGFβ1 signaling decreased the EMT-associated gene expression, and cancer cell invasion." (PMID 26152796, 2015). "Deregulation of EGF and TGFB1 expression levels could influence the normal cellular homeostasis and also influence cancer progression." (PMID 25909813, 2014). "Long-term reciprocal interactions between cancer cells and fibroblasts, which are a source of TGFβ1 production, give rise to an altered cancer cell phenotype that may affect stromal components." (PMID 25202359, 2014).
cancer (continued). "As with chronic irradiation, PPARβ/δ expression and activity were enhanced in the skin of wild-type animals upon acute UV exposure, especially in the epithelial compartment where carcinomas arise, as documented by the stimulation of two known target genes, Tgfβ1 and Plin2." (PMID 24203162, 2014). "The TGFβ1 production from cancer cells was measured by ELISA." (PMID 23690936, 2013). "Cancer-associated fibroblasts (CAFs) affect tumorigenesis by creating an environment primed for growth and invasion through the secretion of factors, including hepatocyte growth factor (HGF) and transforming growth factor β1 (TGFβ1)." (PMID 24137336, 2013). "Importantly for a cancer target, αvβ6 is only found at very low levels in normal tissue; its expression has been reported to regulate wound healing and activation of TGFβ1 in response to injury and inflammation in the lungs." (PMID 24023846, 2013). "Studies have demonstrated that the TGFβ1-Smad signalling pathway is involved in the progression and prognosis of several types of carcinomas, including oesophageal, colorectal and gastric carcinoma." (PMID 24137336, 2013). "Indeed, in a previous study on a series of colorectal cancers, at different stages, from I to IV, the amount of TGFβ1 was found significantly increased only in the most advanced cancer stage." (PMID 22848630, 2012). "The mouse skin carcinogenesis model has been a useful tool to dissect the function of this pathway in cancer pathogenesis, with transgenic and null mice as well as small molecule inhibitors to alter the function of the TGFβ1 pathway and assess the effects on cancer development." (PMID 23326666, 2012). "Under experimental conditions where endogenous TGFβ1 is added in vitro to normal or carcinoma cells lines, activated TGFβ1 levels may be increased for extended periods of time." (PMID 22844446, 2012). "On the other hand, many cancers overexpress TGFβ1 and TGFβ signaling can promote carcinogenesis and cancer progression by inducing angiogenesis, cancer cell invasion into the extracellular matrix, epithelial-to-mesenchymal transition (EMT) and metastasis, as well as by repressing immunosurveillance." (PMID 21297902, 2010). "Thus, our results indicated that doxorubicin or TGFβ1 treatment has the potential to generate drug resistant cancer cells with stem/progenitor cell features." (PMID 20442777, 2010). "Thus, the ligand TGFβ1 and its receptors TGFβ receptor (TGFβR) type I and II have been pursued as anti-cancer targets." (PMID 20576088, 2010). "Our earlier studies have shown that reactive stroma initiates at foci of early premalignant prostatic intraepithelial neoplasia (PIN) in human prostate gland and co-evolves with the development of carcinoma and expression of transforming growth factor beta 1 (TGF-β1) in PIN epithelium." (PMID 21060787, 2010). "For example, TGFB1 and VEGF variants are associated with altered protein products, which may contribute to variation in individual susceptibility to cancer and clinical outcomes." (PMID 19566948, 2009). "TGFβ1 has previously been shown to induce EMT in the alveolar-type cancer cell line, A549." (PMID 19857272, 2009). "For example, some TGFB1 and VEGF variants are associated with protein functions, which may contribute to an individual's susceptibility to cancer." (PMID 19835575, 2009). "With regard to TGFβ1, lower levels were seen in patients with cancer compared with controls." (PMID 12778073, 2003). "A lower TGFβ1 level was noted in patients with carcinoma over the controls." (PMID 12778073, 2003). "Similarly, other publication showed that Nudifloside, a derivative of Callicarpa nudiflora used in China as a traditional folk medicine, can reverse the EndMT (through inhibiting Ezrin phosphorylation) induced by TGFβ1 122, thus revealing a potential anti-EndMT drug for cancer therapy." (PMID 40083695, 2025).